IL7 (interleukin 7)
Diseases named in the same sentence as IL7 in open-access papers (continued):
Sharing a sentence is not in itself a finding about the gene and the disease.
rheumatoid arthritis (59 papers, 2005 to 2025). A chronic, systemic autoimmune disorder characterized by inflammation in the synovial membranes and articular surfaces. "Abnormal expression levels and dysfunctional behavior of IL-7 or its signaling pathway components are frequently linked to various chronic inflammatory autoimmune disorders, rheumatoid arthritis (RA) being one such prominent example." (PMID 39496049, 2024). "IL-7-associated homeostatic expansion is also linked to inflammatory diseases, including graft-vs.-host-disease, rheumatoid arthritis, and multiple sclerosis." (PMID 31024566, 2019). "IL-7 is known to have an important role in the development of rheumatoid arthritis, while IL-15 has been associated with the development of joint inflammation." (PMID 19156204, 2009). "TNF-α enhancement by IL-7 is also present in other pathological conditions, characterized by a local and/or systemic bone loss, such as rheumatoid arthritis or postmenopausal osteoporosis." (PMID 17205128, 2006). "Furthermore, IL-7 is linked to osteoclastogenesis and fibroblast activation, processes involved in tissue destruction in chronic inflammatory diseases like rheumatoid arthritis, ankylosing spondylitis, and inflammatory bowel disease." (PMID 40142185, 2025). "As IL-7 has been implicated as a causative factor in autoimmunity, including rheumatoid arthritis, unregulated control of CD317+ cell numbers and function may also contribute to disease onset and progression." (PMID 26070611, 2015). "Furthermore, IL-7 signaling may affect the migration of peripheral blood monocytes in rheumatoid arthritis (RA), a chronic autoimmune disorder caused by ERK." (PMID 34956167, 2021). "There is growing evidence that raised expression levels of IL-7 and CD127 are linked to various immune-mediated diseases such as rheumatoid arthritis and psoriasis." (PMID 38590608, 2024). "GSEA analysis showed more than half of upregulated pathways, including cytokine-cytokine receptor interaction, inflammatory bowel disease, and rheumatoid arthritis, common in IL-7-Tph and RA-Tph cells." (PMID 39554252, 2024). "IL-7 has been found to effectively stimulate the production of IFNγ and TNFα in rheumatoid arthritis and IL-17 in spondyloarthritis." (PMID 37047315, 2023). "It has been reported that expression of IL-7 and its receptor are increased in rheumatoid arthritis synovial fluid and fibroblasts, compared to normal cells." (PMID 37217704, 2023). "IL-7 and IL-7R signalling pathways are important for T cell population maintenance and are involved in many inflammatory conditions, such as diabetes and rheumatoid arthritis." (PMID 34371826, 2021). "Other cytokines that are deregulated in chronic inflammatory diseases (e.g. rheumatoid arthritis, RA) and are currently targeted in patients are IL-7 and IL-15 that belong to the common gamma chain cytokine family." (PMID 32647892, 2021). "In humans, IL-7 and its receptor (IL-7R) are increased in diseases characterized by inflammation such as atherosclerosis, rheumatoid arthritis, psoriasis, multiple sclerosis, and inflammatory bowel disease." (PMID 23057802, 2012). "Accordingly, the effect of IL-7 and IL-7R in rheumatoid arthritis is worth exploring." (PMID 37217704, 2023). "Coincidently, a recent study of rheumatoid arthritis (RA) showed that the high responsiveness to IL-7 stimulation together with the synergy of IL-7 and M1-promoting factors (e.g., MIP-1b, TNF-a) can enhance the expression of joint myeloid IL-7R and further exacerbate arthritis." (PMID 32117217, 2020). "In arthritis, IL-7 might play an important role since its levels are reported elevated in the synovial fluid and serum from rheumatoid arthritis (RA) patients, in comparison with osteoarthritis (OA) patients." (PMID 31209645, 2019). "On multivariate analysis the changes in the post-therapy concentrations of ACPA, IL-7 and G-CSF (p < 0.05), may have been influenced by the presence of rheumatoid nodules." (PMID 26021985, 2015).
rheumatoid arthritis (continued). "Taken together the data suggest that as in ovariectomy and rheumatoid arthritis IL-7 may play a critical role in the enhanced bone resorption and suppressed bone formation associated with multiple myeloma." (PMID 24278766, 2013). "IL-7 is known to be an inflammatory mediator associated with arthritic diseases, and MIF is a proinflammatory cytokine involved in several inflammatory disorders, including rheumatoid arthritis, inflammatory bowel disease, psoriasis, and multiple sclerosis." (PMID 23533306, 2013). "Moreover, IL-7 has been described to drive inflammation in several prototypic inflammatory conditions such as rheumatoid arthritis or atherosclerosis." (PMID 21949827, 2011). "IL-7 has also been suggested to play a role in rheumatoid arthritis based upon the observation of increased levels of the cytokine in this patient population, its ability to induce TNFα and induction of bone loss by stimulation of RANKL-dependent osteoclastogenesis." (PMID 18234077, 2008). "Moreover, IL-7 mediates the production of pro-inflammatory cytokines by intra-articular T cells, indicating that IL-7 contributes to increased Th1 responses in patients with rheumatoid arthritis." (PMID 37373104, 2023). "We previously demonstrated reduced levels of circulating IL-7 in rheumatoid arthritis (RA), although high amounts are expressed in joints, suggesting differences between systemic and synovial effects." (PMID 25533722, 2014). "Interestingly, high levels of IL-7 have also been reported in rheumatoid arthritis and may contribute to the cycle of inflammation and/or bone loss." (PMID 24278766, 2013). "In patients with rheumatoid arthritis, rituximab significantly reduced serum concentrations of CRP, RF, anti-CCP, IL-2, IL-6, IL-7, IL-10, and ESR." (PMID 41057909, 2025). "Thus, elevated levels of IL-7 and IL-15 in synovia, along with elevated levels of inflammatory cytokines, may have additional negative effects on the functional activity of Treg cells in rheumatoid arthritis." (PMID 33809452, 2021). "High levels of IL-7 are found in several arthritic conditions, including rheumatoid arthritis (RA)." (PMID 22676399, 2012). "In patients with OA, the immunoexpression levels of TNF-α, IL-1β, IL-7, MMP-1, MMP-2, and MMP-3 were significantly higher in patients with active rheumatoid arthritis (RA), whereas the immunoexpression levels of IL-1, IL-2, IL-4, IL-6, IL-15, IL-18, and MMP-3 were not statistically different." (PMID 40004793, 2025). "Moreover, high levels of inflammatory/arthrogenic factors, including cytokines (TNF-α, IL-6, IL-7, IL-15, and BAFF) and chemokines (CCL-2, CCL-5, and CXCL-10) have been reported in the serum and/or synovia of rheumatoid arthritis patients." (PMID 38720890, 2024). "The effect of IL-7 on CD28null T cells has not been previously studied in any disease, while the effect of IL-15 on CD28null T cells has been investigated in multiple sclerosis, elderly individuals, and rheumatoid arthritis." (PMID 32647892, 2021). "However, it is noteworthy that pro-inflammatory cytokines and chemokines, i.e., interleukin-7, interleukin-12 and CXC motif chemokine 13, associated with systemic inflammatory diseases such as systemic lupus erythromatosus or rheumatoid arthritis were not increased among POTS-positive patients." (PMID 31001074, 2019).
breast carcinoma (58 papers, 2006 to 2026). "In breast cancer, elevated IL-7 levels have been associated with enhanced tumor growth and poor prognosis." (PMID 39334861, 2024). "High expression of IL‐7 was already shown to be associated with lower survival of patients with other cancers such as lung cancer or breast cancer." (PMID 36054746, 2022). "IL-7-expressing cancer-associated fibroblasts (CAFs) promoted breast tumor growth and provided critical niches for the maintenance of breast cancer stemness." (PMID 35735628, 2022). "Reported data represents the observed association between use of insulin secretagogues preceding breast cancer diagnosis and GM-CSF, G-CSF and IL-7 profiles at the time of cancer diagnosis in women with diabetes mellitus." (PMID 28275660, 2017). "Elevated IL-7 levels have been associated with poor survival in for example ovarian cancer and breast cancer patients." (PMID 23383336, 2013). "Moreover, recent data show that IL7 is part of a cytokine signature linked to metastasis in breast cancer patients." (PMID 38055067, 2023). "We determined the effects of 12-weeks supervised exercise training on the frequency of T-cell subtypes in peripheral blood and their relationships with circulating levels of the muscle-derived cytokines (i.e. ‘myokines’) IL-6, IL-7, IL-15 and osteonectin in older women at high risk of breast cancer." (PMID 35321743, 2022). "Furthermore, IL-7 expressed by cancer-associated fibroblasts stimulated the stemness and tumor growth of breast cancer." (PMID 35735628, 2022). "Il7 is a hematopoietic factor secreted by mesenchymal cells in the bone marrow and thymus, whose variant Il7δ5 could induce human breast cancer cell proliferation and cell cycle progression in a PI3K-Akt-dependent manner." (PMID 34545275, 2021). "Additionally, IL-7 is the primary driver of T and B cell differentiation, maturation, and response (Corfe and Paige, 2012) and its elevated levels have been associated with poor prognosis in breast cancer." (PMID 28275672, 2017). "Recent studies on breast cancer describe a quantitative association between the IL-7 signalling complex and some clinico-pathological parameters: there is a trend towards a higher expression of IL-7 and molecules of its signalling pathway in breast cancer patients with poor prognosis." (PMID 17205128, 2006). "TRUCK CAR T-cells incorporating various soluble cytokines, including IL-15, IL-7, and IL-18, have been explored for breast cancer." (PMID 38201551, 2023). "The signaling responsiveness of p-STAT5 to IL-7 stimulation was tested in CD4+ and CD8+ T cells; while all healthy donors (19/19) responded to IL-7, only 6/19 breast cancer patients responded to cytokine stimulation." (PMID 37741983, 2023). "The results of the forward MR analysis showed a potential link between IL-5, IL-7, and IL-16 and an increased risk of HER2-positive breast cancer." (PMID 37910571, 2023). "Together, the data suggested that IL7 produced and secreted by lymphatic endothelial cells exposed to TGFβ1 can act as a chemotactic factor for breast cancer cells with mesenchymal properties." (PMID 38055067, 2023). "Our findings demonstrate that IL-5, IL-7, and IL-16 are risk factors for HER2-positive breast cancer, with varying degrees of increased probability of HER2-positive breast cancer associated with elevated levels of these inflammatory cytokines." (PMID 37910571, 2023). "Exogenous IL-7 promotes breast cancer growth via the JAK/STAT pathway and lung cancer cell growth via the c-Fos/c-Jun pathway." (PMID 36672342, 2023). "In preclinical breast cancer studies, IL-7 is often combined with chemokines such as CCL19 and CCL21 to improve the chemotaxis of CAR T cells and other immune cells to the tumor site." (PMID 38201551, 2023). "As a cytokine therapy for cancer treatment, IL-7 exerts superior activity to induce the expansion of specific T cells against breast carcinoma than IL-2, highlighting its antitumor adjuvant molecular role in oncology." (PMID 36389666, 2022).
breast carcinoma (continued). "Intriguingly, antigen-activated T lymphocytes incubated with IL-7 and IL-15 exhibited a more robust capability to induce regression of melanoma and 4T1 mammary carcinoma in comparison to IL-2 alone." (PMID 36389666, 2022). "TSLP is an interleukin-7 (IL-7)-like cytokine that is involved in the progression of various cancers and is a key mediator of breast cancer progression." (PMID 35472078, 2022). "Aberrantly elevated expression of IL-7 and its signaling complex including Jak-3 and PI3-K is associated with aggressive human breast cancer and IL-7 significantly accelerates the growth of breast cancer cells in vitro." (PMID 34575268, 2021). "Beyond hematological cancer, high expression of IL-7 and IL-7R in tumor tissues of breast and lung cancer patients is positively correlated with more aggressive breast cancers and poor survival." (PMID 34575268, 2021). "In another breast cancer study, levels of IL-7, IL-8, IL-13, macrophage migration inhibitory factor (MIF), and TNF-β were increased, whereas those of CTACK, G-CSF, HGF, IL-1β, and TNF-α were decreased after IORT exposure." (PMID 34641806, 2021). "MUC1 CAR T with a cytokine switch receptor of IL4 receptor extracellular domain fused to an IL7 intracellular signaling domain can proliferate and suppress tumor growth in mice breast cancer model." (PMID 33381115, 2020). "Again, tumor growth was significantly reduced when Il7-expressing CAFs were ablated indicating that a subset of tumor fibroblasts can regulate the growth of mammary carcinoma cells." (PMID 29632733, 2018). "DLN lymphocytes were antigen-sensitized with 4T1 mammary carcinoma 10 days prior to harvest, activated with B/I, and expanded in culture for 7 days with either IL-2, IL-21, IL-2/21, IL-7/15, or IL-7/15/21." (PMID 28146052, 2017). "DLN T cells activated with B/I and cultured with IL-2, IL-21, IL-2/21, IL-7/15 or IL-7/15/21 for 7 days were harvested and cultured for 24 h alone or with irradiated 4T1 murine mammary carcinoma cells to stimulate IFN-γ release." (PMID 28146052, 2017). "This is in contrast to what we found with the B16 melanoma model, but similar to our recent observations comparing IL-2 and IL-7/15 in the 4T1 mammary carcinoma model." (PMID 28146052, 2017). "Combined injection of IL-7 and IL-15 into breast cancer lesions after radiofrequency thermal ablation (RFA) can reduce the number of MDSCs, and inhibit the growth and metastasis of breast cancer." (PMID 27542274, 2016). "In breast cancer, IL-7 stimulates invasion and secretion of the lymphangiogenic factors VEGF-C and VEGF-D." (PMID 26320187, 2015). "In murine mammary carcinoma, the administration of IL-7 and IL-15 after radiofrequency thermal ablation (RFA) resulted in a relapse-free survival and showed inhibition of metastatic nodules in their lungs." (PMID 25955647, 2015). "The interleukin-7 (IL7) ligand has been previously implicated as an inducer of tumor growth in lymphoblastic leukemia, prostate cancer, breast cancer, and colorectal cancer." (PMID 23762861, 2013). "IL-7 correlates with lymphatic metastasis in breast cancer patients suggesting that this results from IL-7 induced tumor lymphangiogenesis." (PMID 22946011, 2012). "For example, CD4+ and CD8+ T-cells isolated from breast cancer patients are less responsive to IL-7, as measured by STAT-5 phosphorylation." (PMID 21920046, 2011). "Potential candidate factors are IL-11 and osteopontin, which were shown to stimulate recruitment and activation of osteoclasts in breast cancer osteolytic metastases, and IL-7 that can stimulate spontaneous osteoclastogenesis in bone metastases." (PMID 17683568, 2007). "With the exception of IL-7, all cytokines that were present in both tissues were significantly overexpressed in breast carcinoma." (PMID 17261184, 2007). "In addition, type I interferon signaling also controls the infiltration of γδT17 cells in breast cancer via IL7." (PMID 38762546, 2024).
breast carcinoma (continued). "Impaired IL-7 signaling was found in T cells from breast cancer patients." (PMID 37741983, 2023). "Therefore, it is essential to conduct further follow-up studies to delve deeper into the impact of interleukins (IL-5, IL-7, IL-16, and IL-10) on the two subtypes of breast cancer (HER2-positive and HER2-negative)." (PMID 37910571, 2023). "However, the precise mechanisms by which IL-5, IL-7, and IL-16 contribute to the initiation and metastasis of breast cancer, either via HER2 or other pathways, remain uncertain." (PMID 37910571, 2023). "Importantly, our study is the first to demonstrate that IL-5, IL-7, and IL-16 play a significant role as risk factors in the development of HER2-positive breast cancer." (PMID 37910571, 2023). "This was confirmed here for Thy1 and Il7 in 4T1 breast cancer TDLNs." (PMID 35362044, 2022). "However, number of T cells expressing CD127 was reduced in peripheral blood of patients with breast cancer, resulting in IL-7 signaling defects." (PMID 35850640, 2022). "Our analysis suggests that CCL19, CCL21 and IL7 signaling play an important role in attracting and activating immune cells in the breast cancer microenvironment and might help convert immune cold cancers to immune hot." (PMID 30967156, 2019). "The data presented here shows the relationship between pre-existing use of insulin secretagogues in women diagnosed with breast cancer and type 2 diabetes mellitus, the GM-CSF, G-CSF and IL-7 cytokine profiles at the time of breast cancer diagnosis, and subsequent cancer outcomes." (PMID 28275660, 2017). "However, studies performed in breast cancer indicate that IL-7 promotes the production of pro-angiogenic factors by tumor cells and proliferation of endothelial cells." (PMID 21943235, 2011). "Previous findings have described IL-7 as fundamental for the activation of myeloid cell populations in mice bearing CT26 tumors and for tumor invasiveness in prostate cancer, while IL-15–dependent signaling in tumor-associated macrophages inhibited CD8+ T cell recruitment in breast cancer." (PMID 39841829, 2025). "In the B16 melanoma system, we have now demonstrated in mammary carcinoma that culturing B/I-activated lymphocytes from tumor-sensitized mice in IL-7/15/21 results in a much higher yield of viable cells than those grown in IL-2, IL-21, IL-2/21 and even IL-7/15." (PMID 28146052, 2017). "In contrast, the receptors for IL7 and IL15 were overexpressed in breast cancer cells with basal-like, mesenchymal properties, compared to luminal cells." (PMID 38055067, 2023). "The results demonstrate the capacity of TGFβ1 to orchestrate crosstalk between tumor cells and lymphatic endothelial cells and warrant further studies to explore the roles of IL7 and IL15 in promoting lymph metastasis of breast cancer." (PMID 38055067, 2023). "Further analysis are warranted to determine the contribution of IL7 and IL15 in mediating lymphatic dissemination of breast cancer cells in vivo." (PMID 38055067, 2023). "In contrast, the receptors for IL7 (IL7R) and IL15 (IL15RA) were significantly overexpressed in basal B compared to luminal breast cancer cells." (PMID 38055067, 2023). "For instance, several studies have demonstrated a noteworthy elevation in the concentrations of IL-5, IL-6, IL-7, and TNF-α in both the pathological tissue and systemic circulation of breast cancer patients, as compared to healthy individuals." (PMID 37910571, 2023). "Meanwhile, other researchers have shown that the IL-7/IL-7R axis contributes to EMT in prostate cancer cells and breast cancer cells." (PMID 36672342, 2023). "Our study reveals a genetic correlation between IL-5, IL-7, IL-16, and HER2-positive breast cancer, providing valuable insights for future research on the pathogenesis and pharmacological intervention of HER2-positive breast cancer." (PMID 37910571, 2023).